GOT1 (glutamic-oxaloacetic transaminase 1)
Diseases named in the same sentence as GOT1 in open-access papers (continued):
Sharing a sentence is not in itself a finding about the gene and the disease.
tumor (89 papers, 2003 to 2025). "Cessation of Dox treatment led to the recovery of GOT1 expression and restored tumor growth, indicating that the growth changes were linked to the levels of GOT1." (PMID 39809754, 2025). "More importantly, a low expression of GOT1/2 in tumor tissues are significantly associated with poor OS in patients with KIRC." (PMID 35562974, 2022). "Both GPC1 and GOT1 genes were upregulated in tumor tissues, and were implicated in poor ESCA prognosis (p < 0.05)." (PMID 35794622, 2022). "Our preliminary work revealed that tumour expression of GOT1 was significantly linked with tumour dedifferentiation, vascular invasion and lymphatic invasion." (PMID 28544376, 2017). "There was uniform upregulation of this gene cluster (which included Adc, Nos2, Ass1, Gch1, Asl and Got1) in both tumor-associated MP and MG and Gr1+ cells." (PMID 27936099, 2016). "Tumor expression of GLUD1 was associated with larger tumor size, while tumor expression of GOT1 was significantly linked with tumor dedifferentiation, vascular invasion, and lymphatic invasion." (PMID 25719198, 2015). "Shorter overall survival was associated with high expression of GLUT1 in tumor (P = 0.002) and GOT1 in tumor (p = 0.030)." (PMID 25719198, 2015). "Tumor expression of GOT1 was significantly linked with tumor differentiation (P = 0.0238), vascular invasion (P = 0.0384), lymphatic invasion (P = 0.0367)." (PMID 25719198, 2015). "Due to some heterogeneity in GOT1 tumors, there is a risk that a mouse may be transplanted with a tumor piece having cells with altered SSTR expression, which was most probably the case in the present study, and explains the lower SSTR2 expression in this non-responding mouse." (PMID 35008397, 2022). "This interaction stabilized GOT1 and regulated glutamine metabolism, thereby promoting tumor proliferation." (PMID 40390008, 2025). "This process is critical for preserving cellular redox balance and supporting tumor cell proliferation, making Got1 a potential molecular target for anticancer therapy." (PMID 40941077, 2025). "In summary, in ICC cells with high expression of ANXA1, ANXA1 further increases the adaptability of Glutamine metabolism mediated oxidative stress by stabilizing ubiquitin proteasome mediated GOT1, thereby promoting tumor growth and proliferation." (PMID 40390008, 2025). "GOT1 subsequently converts oxaloacetate and α-ketoglutarate (α-KG) into intermediates that fuel tumor cell proliferation." (PMID 40390008, 2025). "Immunohistochemistry confirmed that the lower expression of GOT1 and ALDH3A1 was consistent with the smaller tumor volume in the Sh1-GOT1 group." (PMID 41327788, 2025). "In the group of ANXA1 knockdown and overexpression of GOT1, tumor formation and growth were restored." (PMID 40390008, 2025). "Overall, AFM images reaffirmed that naringenin can stably bind to GOT1 protein, influencing its function and contributing to anti-tumor effects." (PMID 40732339, 2025). "Collectively, these results suggest that naringenin targets the GOT1 protein to inhibit the glutamine metabolic pathway, thereby suppressing tumor development in CRC." (PMID 40732339, 2025). "Mechanistically, the abnormal proliferation of these tumor cells was due to the reduction of Asp synthesis through inhibiting Gln oxidation and attenuating reductive carboxylation following GOT1 deletion, which disrupted nucleotide generation within the cells." (PMID 39777342, 2024). "Lastly, GOT1 is upregulated in PC tissues, and exosomal GOT1 suppresses tumor cell ferroptosis, accelerating PC progression through activating Nrf2/HO-1 axis and upregulating CCR2 expression." (PMID 39113699, 2024). "For example, circ-MBOAT2 silencing downregulated the expression of GOT1 via sponging miR-433-3p, modulating the tumor development of PDAC." (PMID 39777342, 2024).
tumor (continued). "A recent study demonstrates that inhibiting GOT1 activity hinders the growth of several pancreatic ductal adenocarcinoma cell lines, primary tumor models, and tumor xenografts." (PMID 36959802, 2023). "Human GOT1 tumor-bearing mice received 30 MBq 177Lu-octreotate or 5 mg/kg A1M or co-treatment with both." (PMID 37076494, 2023). "When GPT1 and GOT1 levels were decreased in mice, fewer tumour metastases were formed by tumour cell injection than in controls." (PMID 37829798, 2023). "RT-qPCR results showed that the abundance of P4HA1, MLLT11, AURKA, and GOT1 were significantly elevated in tumor tissues." (PMID 35558559, 2022). "Studies on colon cancer cell lines have found that overexpression of GOT1 caused cells to synthesize nicotinamide adenine dinucleotide phosphate (NADPH) to regulate the levels of reactive oxygen species and promote tumour growth." (PMID 34474530, 2022). "Through immunohistochemical staining sections of tumor tissues and adjacent tissues, we observed that the number of GOT1 positive cells in tumor tissues was more than that in adjacent tissues." (PMID 36497150, 2022). "GOT1 knockdown led to an approximate sixfold reduction in tumor volume in this model, indicating that GOT1 aids in tumor growth." (PMID 35147163, 2022). "Consistent with the RT-qPCR results, Western blot also showed that the protein levels of P4HA1, MLLT11, AURKA, and GOT1 were markedly higher in the tumor tissues than those in the paratumor tissues." (PMID 35558559, 2022). "In vivo findings demonstrate that knockdown of GOT1 expression delay tumor progression in nude mice." (PMID 36497150, 2022). "Studies on GOT1 have mainly focused on tumours, and only a few studies have investigated the participation of GOT1 in lipid synthesis." (PMID 34474530, 2022). "Since GOT1 cell proliferation is slow, most GOT1 animal studies are performed in the model based on serial transplantation of small tissue pieces from one tumor to several younger mice, which was the case in the present study." (PMID 35008397, 2022). "The immunohistochemistry images from The HPA database showed that ACO1 and GOT1 levels were lower in tumor compared to normal tissues." (PMID 36733386, 2022). "Culturing cells in tumor-relevant cystine potentiated GOT1 knockdown in a time- and dose-dependent manner, in agreement with our pharmacological studies." (PMID 34381026, 2021). "GOT1 knockdown was demonstrated by immunoblot analysis on homogenized tumor tissue and biochemically via the induction of aspartate." (PMID 34381026, 2021). "In this research, we found circ-MBOAT2 silencing suppressed tumor progression and glutamine catabolism via downregulating GOT1 through sponging miR-433-3p." (PMID 33832516, 2021). "The role of GOT1 in ferroptosis has been the subject of previous study in several other tumor types." (PMID 34381026, 2021). "GOT1 knockdown significantly decreased the viability of both LNCaP and PC3 cells, consistent with previous reports that GOT1 repression suppresses tumor growth, and the invasiveness and colony-forming ability of PC3 cells." (PMID 32111915, 2020). "These insights were leveraged in PDA, where we demonstrate that radiotherapy potently enhanced the effect of GOT1 inhibition on tumor growth." (PMID 31908776, 2020). "Knockdown of GOT1 has been known to suppress tumor growth, invasiveness, colony-forming ability, and also cell viability of PC-3 (androgen independent) and LNCaP (androgen independent) cells." (PMID 32322560, 2020). "The screening revealed that inhibitors of Hsp90 can potentiate the tumour cell-killing effect of radiation in a synergistic fashion (GOT1; false discovery rate <3.2 × 10−11)." (PMID 30730850, 2019). "Taken together, our findings identify AO as a potent bioactive inhibitor of GOT1 and a novel anti-tumour agent for PDAC therapy." (PMID 31470862, 2019).
tumor (continued). "Generation of GOT1 xenografts in nude mice is performed by first establishing a tumor into a few mice, by subcutaneous injection of cells from in vitro culture." (PMID 30895393, 2019). "The potential for Hsp90 inhibitor ganetespib to enhance the anti-tumour effect of 177Lu-octreotate in an in vivo setting was studied in the somatostatin receptor-expressing GOT1 xenograft model." (PMID 30730850, 2019). "Adaptation to these changes is important for survival of tumor cells and published data have demonstrated that GOT1 plays a key role in the metabolic reprogramming and maintenance of redox homeostasis in cancer cells." (PMID 29751795, 2018). "GOT1 expression levels and correlation with survival rates were analysed in selected tumor databases." (PMID 29751795, 2018). "Consistent with our in vitro results, GOT1 knockdown significantly decreased ddp-resistant tumor growth in vivo." (PMID 29511244, 2018). "In summary, combination therapy of GOT1 tumors in nude mice using sonidegib and 177Lu-octreotate resulted in a profound reduction in tumor volume shortly after treatment start, similar to the effect of 177Lu-octreotate monotherapy." (PMID 28789624, 2017). "The growth rate of GOT1 tumors differs much between animals within a transplantation batch, which results in a large variation in tumor sizes at a certain time point." (PMID 28097640, 2017). "Shorter overall survival was associated with high expression of GLUT1 in tumor (P = 0.002), GOT1 in tumor (p = 0.030), and LC3 in tumor (p = 0.009)." (PMID 25719198, 2015). "Clinical PDA cases expressing a high GOT1 to GLUD1 or GOT2 to GLUD1 ratio in the tumor have worse outcomes." (PMID 26462257, 2015). "Here, we report that assessing the GOT1 status in tumor tissue samples has the potential of becoming such a biomarker." (PMID 25595905, 2015). "In GOT1 xenografts, untreated tumours showed 29% K8 expression, and this increased significantly to 58% after 3 days of treatment (p < 0.05; n = 3)." (PMID 22214480, 2011). "We also confirmed TS1 binding in a177Lu-DOTA-Tyr3-octreotate-treated xenografts of the midgut carcinoid cell line GOT1 and in tumour biopsies from seven patients with small-cell carcinoma in pulmonary bronchi." (PMID 22214480, 2011). "A high concentration of 123I was maintained in GOT1 tumours and adrenals, which expressed VMATs, but rapidly decreased in all other tissues." (PMID 14520475, 2003). "In nude mice, bearing the human transplantable midgut carcinoid GOT1, all organs and xenografted tumours accumulated 123I after i.v. injection of 123I-MIBG." (PMID 14520475, 2003). "Mechanistically, ANXA1 promotes the binding of USP5 to GOT1, thus preventing the degradation of GOT1 via the ubiquitin-proteasome pathway and promoting glutamine metabolism to enhance the oxidative stress adaptation of tumor cells and promote tumor growth." (PMID 40390008, 2025). "Therefore, targeting the inhibition of GOT1 to disrupt tumor glutamine-mediated metabolic reprogramming represents an important strategy for screening promising anti-tumor drug candidates." (PMID 40732339, 2025). "Next, we further explored whether ANXA1 could affect GOT1-mediated glutamine metabolism and its mechanism of promoting tumor cell proliferation." (PMID 40390008, 2025). "Under complete culture medium conditions, compared with the control group, ANXA1 knockdown cells showed significant growth, and overexpression of GOT1 could almost rescue ANXA1 knockdown tumor inhibition." (PMID 40390008, 2025). "Notably, knockdown of EPRS or LARS did not affect global protein synthesis, while their effects on MAS and tumour progression are exerted, at least in part, through GOT1 or MDH1." (PMID 38769668, 2024). "GOT1 also plays an important role in an acidic tumor microenvironment." (PMID 39777342, 2024). "SIRT5, a tumor suppressor of PC, reduces non-canonical metabolism of Gln by deacetylating GOT1 to inhibit its activity, which is associated with a favorable prognosis." (PMID 36699061, 2022).
tumor (continued). "Besides that, the contents of ROS, MDA and Fe2+ were decreased in the tumor tissues of mice with knockdown of GOT1 expression relative to those in the tumor tissues of control mice." (PMID 36497150, 2022). "Another scholar found that ziprasidone could induce glutamine metabolism disorder and redox state imbalance of PDAC cells by targeting GOT1, thereby inhibiting tumor cell proliferation, migration and inducing cell apoptosis." (PMID 36497150, 2022). "Furthermore, transcriptomic analyses of GOT1 tumor tissues demonstrated higher proapoptotic and antiproliferative responses after the ‘priming schedule’, as well as increased stress response and initiation of cell cycle arrest." (PMID 35008397, 2022). "The GOT1 tumor model is unique, since it is probably the only small-intestinal NET cell line that could be transplanted to nude mice with preserved neuroendocrine features and receptor expression." (PMID 35008397, 2022). "The first in vivo study in the GOT1 animal model showed that curative amounts of 177Lu-octreotate resulted in lower expression of SSTRs during the time period studied: 4 h to 13 days (reflected by lower tumor uptake of subsequently injected 111In-octreotide)." (PMID 35008397, 2022). "Next, tumor tissues from both groups of mice were collected and subjected to immunohistochemical histostaining, and we observed a significant decrease in the number of cells positive for GOT1, CCR2, Nrf2 and HO-1 proteins in tumor tissue sections from mice with knockdown of GOT1 expression." (PMID 36497150, 2022). "GOT1 inhibitors Aspulvinone O, Ziprasidone, and Aspulvinone H induced the disturbance of Gln metabolism and imbalance of redox status in PC cells, thereby inhibiting cancer cell proliferation, and showed significant antitumor effects in xenograft tumor models." (PMID 36699061, 2022). "Moreover, Western blotting results suggested that knockdown of GOT1 expression similarly reduced GPX4 protein expression in tumor tissues." (PMID 36497150, 2022). "In addition, we selected three pairs of tumor tissues and adjacent tissues to examine, and the results of Western blotting indicated that GOT1 expression was increased in tumor tissues compared with adjacent tissues." (PMID 36497150, 2022). "Moreover, exosome treatment enhanced the ability of cell invasion and clonogenicity, and the transfection of si-GOT1 reversed the effect of exosomes, but in the effect of NK-252, the ability of tumor cell invasion and clonogenicity was again enhanced." (PMID 36497150, 2022). "In addition, rescue experiments were employed to illustrate the effects between miR-433-3p and circ-MBOAT2 or GOT1 on tumor evolution and glutamine metabolism." (PMID 33832516, 2021). "The inhibition of de novo GSH biosynthesis with BSO also potentiated tumor inhibition by GOT1." (PMID 34381026, 2021). "GOT1 could also accurately classify samples according to the tumor site in THCA (ROC curve; AUC = 73.6%)." (PMID 34186243, 2021). "Moreover, HIFɑ can inhibit the proliferation of tumor cells by inhibiting the synthesis of aspartate; however, in our study, we found that GOT1 was a protective factor, with higher expression in the low-risk group than in the high-risk group." (PMID 33228592, 2020). "Another study has demonstrated the importance of GOT1 in tumor growth in vivo tumor models of CRC." (PMID 32322560, 2020). "Aspartate aminotransferase (GOT1/2), important regulators of levels of glutamate which contributes to glucose synthesis and gluconeogenesis, have been found to be upregulated in various tumor cells." (PMID 33173435, 2020). "RNA microarray analysis was performed on tumor samples from GOT1-bearing BALB/c nude mice treated with a 5 MBq priming injection of 177Lu-octreotate followed by a second injection of 10 MBq of 177Lu-octreotate after 24 h and killed after 1, 3, 7, and 41 days after the last injection." (PMID 30895393, 2019).
tumor (continued). "In addition to regulating amino acid metabolism, GOT1 also promotes tumor cell proliferation by maintaining intracellular redox balance." (PMID 31010998, 2019). "The GOT1 cell line originated from a tumour that had loss of whole chromosome 18 and like GOT1, with predominance of losses and without gains of whole chromosomes (data not shown)." (PMID 29444910, 2018). "Furthermore, we measured the inhibition of HIF‐2α and GOT1 in the xenotransplanted tumours derived from the sh‐HIF‐2α and sh‐control groups, respectively." (PMID 28544376, 2017). "Additionally, KRAS G12D mutation regulates the transcription of key metabolic enzymes such as glutamate dehydrogenase (GLUD1) and aspartate aminotransferase (GOT1), enabling tumor cells to meet carbon and nitrogen demands for rapid proliferation and macromolecular synthesis." (PMID 40427667, 2025). "In summary, these results indicate that ANXA1 can regulate the expression of GOT1, promote the adaptive ability of glutamine metabolism mediated tumor associated oxidative stress, further promote tumor growth, and inhibit ANXA1 combined with glutamine deficiency to inhibit tumor growth." (PMID 40390008, 2025). "In vivo studies showed that knockdown of GOT1 expression inhibited tumor formation compared with tumor tissues formed upon exosome induction, which was mediated by promoting ferroptosis via suppressing the protein expression of GOT1, CCR2, Nrf2 and HO-1 in tumor tissues." (PMID 36497150, 2022). "In addition, treating cells with aminooxyacetate to inhibit GOT1 could induce apoptosis in tumour cells, and targeting GOT1 could selectively kill tumour cells." (PMID 34474530, 2022). "However, GOT1 inhibition uniquely increased the time to tumor tripling in PDA." (PMID 31908776, 2020). "Recently, expression microarray analysis of GOT1 tumors was presented, demonstrating radiation-induced apoptosis as an early response after a non-curative 177Lu-octreotate administration, followed by pro-survival transcriptional changes in the tumor during the regrowth phase." (PMID 30895393, 2019). "We hypothesized that GOT1 can be used by tumor cells to deal with unfavorable growth conditions." (PMID 29751795, 2018). "Furthermore, the tumor take is relatively low for GOT1, which also has a long tumor doubling time." (PMID 28097640, 2017). "However, overexpression of GOT1 could reverse this effect and promote tumor growth in vivo." (PMID 40390008, 2025). "We also investigated the expression of GPX4, 4-HNE, GOT1, NCOA4, FTH, and LC3B in tumor tissues using IHC staining." (PMID 36387145, 2022). "One explanation can be a higher accumulation in tumor tissue due to a therapeutic effect resulting in tumor volume reduction, a phenomenon we have observed in our previous studies on the human small intestinal NET GOT1 model." (PMID 34433438, 2021). "Based on these results, we then explored the utility of GOT1 inhibition as a radiosensitizing strategy in PDA and CRC tumor models in vivo." (PMID 31908776, 2020). "We were able to identify 28 and 37 inhibitors, respectively, in screenings of GOT1 and P-STS cells that significantly synergised with radiation (P < 0.05) in killing tumour cells in vitro (see section on supplementary datagiven at the end of this article)." (PMID 30730850, 2019). "In vivo studies using the human small intestine NET model, GOT1 xenotransplanted to nude mice, have also shown an increased binding of 111In-DTPA-octreotide in tumor tissue after injection of 177Lu-octreotate." (PMID 30895393, 2019). "In GOT1 and BON-1, we also found expression of SSTR2, a major target for symptomatic treatment of hormonal symptoms, tumour imaging and peptide receptor radiotherapy in GEPNET patients." (PMID 29444910, 2018). "We detected an increased exposure of the TS1 target, K8 in particular in small necrotic areas in tumours after 5 and 3 days of177Lu-DOTA-Tyr3-octreotate treatment in both the NCI-H69 SCLC and midgut GOT1 xenografts." (PMID 22214480, 2011).